DHX40 (DEAH-box helicase 40)
Description:
Probable ATP-dependent RNA helicase.
Synonyms: DDX40; ARG147; PAD; FLJ22060
Tractability: PROTAC: ubiquitination databases record sites on it; its protein half-life has been measured.
Target class: Enzyme; Hydrolase
Gene: Protein-coding gene on chromosome 17 (59,565,558 to 59,610,481, forward strand). Ensembl gene ENSG00000108406.
Subcellular location (Human Protein Atlas): Nucleoplasm
Gene Ontology:
Molecular function: protein binding; 3'-5' RNA helicase activity; ATP binding; ATP hydrolysis activity; nucleic acid binding; RNA helicase activity
Biological process: mRNA splicing, via spliceosome
Cellular component: spliceosomal complex
Genetic constraint (gnomAD): Loss-of-function variants: 26 observed, 63.38 expected, observed/expected ratio (o/e) 0.41, 90% interval 0.3 to 0.57. The upper end of that interval is the gene's LOEUF score, 0.57, which puts it in group 2 of 6, group 1 being the genes least tolerant of losing a copy. Missense variants: 436 observed, 705.07 expected, observed/expected ratio (o/e) 0.62, 90% interval 0.57 to 0.67. Synonymous variants: 218 observed, 238.65 expected, observed/expected ratio (o/e) 0.91, 90% interval 0.82 to 1.02.
Homologues: Orthologues: macaque DHX40 (99% identical), pig DHX40 (99% identical), dog DHX40 (99% identical), rabbit DHX40 (98% identical), mouse Dhx40 (97% identical), rat Dhx40 (97% identical), guinea pig DHX40 (96% identical), tropical clawed frog dhx40 (63% identical), zebrafish dhx40 (62% identical), chimpanzee DHX40 (12% identical). Paralogues in human: DHX8 (35% identical), DHX16 (34% identical), DHX38 (32% identical), DHX15 (32% identical), DHX35 (29% identical), DHX33 (29% identical), DHX57 (28% identical), DHX36 (28% identical), DHX37 (28% identical), YTHDC2 (27% identical), DHX34 (27% identical), DHX29 (25% identical), and 6 more.
Diseases named in the same sentence as DHX40 in open-access papers:
DHX40 is named in the same sentence as 7 diseases in open-access papers, as found by Europe PMC text mining. Sharing a sentence is not in itself a finding about the gene and the disease. The quoted sentences say what the papers report.
breast tumor (2 papers, 2007 to 2008). "Finally, our data revealed seven other protein coding genes (FAM33A, DHX40, CLTC, PTRH2, TMEM49, TUBD1, ABC1, and USP32) that have not been implicated previously in 17q23 studies, but whose expression was clearly associated with copy number status in primary breast tumours." (PMID 17353917, 2007).
melanoma (1 paper, 2022). A malignant, usually aggressive tumor composed of atypical, neoplastic melanocytes. "We showed that SDT-mRNA can indeed be used for both purposes using known mutated antigens, including DHX40 and Melan-A/Mart-1 (A27L), and four HLA-A2-restricted candidate neoantigens that were identified in melanoma tumor sample using NGS and the ImmunoEngine pipeline developed by myNEO." (PMID 36159589, 2022).
scoliosis (1 paper, 2021). A congenital or acquired spinal deformity characterized by lateral curvature of the spine. "Some candidates, such as DHX40, NBPF20, RASA2, and MYSM1, have been found to be associated with syndromes with scoliosis or implicated in bone/spine development." (PMID 34440387, 2021).
tumor (3 papers, 2007 to 2023). "To functionally characterize the DHX40 variant, we evaluated its expressional consequences on RNA and protein level, undertook tumor studies to analyze somatic variants, changes in gene methylation and DHX40 protein expression, and conducted siRNA analyses of cell lines." (PMID 37696923, 2023). "Interestingly, a duodenum adenoma from F32 showed a mosaic loss of DHX40 protein by immunohistochemical analysis, suggesting that biallelic defects could be present, but in only a small proportion of tumor cells." (PMID 37696923, 2023).
cancer (1 paper, 2019). A tumor composed of atypical neoplastic, often pleomorphic cells that invade other tissues. "MethylMix-PA also found hyper-methylation of DHX40 which has an unclear link to cancer; although it is of note that RNA splicing proteins—like DHX40 –are highly stable, perhaps explaining the particularly stronger effect of DNA methylation on protein abundance than mRNA." (PMID 31356589, 2019).
neurodegenerative disease (1 paper, 2022). A disorder of the central nervous system characterized by gradual and progressive loss of neural tissue and neurologic function. "The ‘Human UP’ genes include FOXP2, MTRNR2L8, DHX40, VPS13B, WDFY2 and PURB, all of which are associated with neurodevelopment or neurodegenerative disease." (PMID 36052683, 2022).
DHX40 also shares sentences with these, for which no sentence is quoted: Cohen syndrome (1 paper).